ETV7 (ETS variant transcription factor 7)
Description:
Transcriptional repressor; binds to the DNA sequence 5'-CCGGAAGT-3'. Isoform A does not seem to have a repressor activity. Isoform C does not seem to have a repressor activity.
Synonyms: TEL2; TELB; TEL-2
Tractability: PROTAC: ubiquitination databases record sites on it.
Gene: Protein-coding gene on chromosome 6 (36,354,091 to 36,387,800, reverse strand). Ensembl gene ENSG00000010030.
Subcellular location: Nucleus
Subcellular location (Human Protein Atlas): Nucleoplasm
Gene Ontology:
Molecular function: DNA-binding transcription repressor activity, RNA polymerase II-specific; protein binding; RNA polymerase II transcription regulatory region sequence-specific DNA binding; sequence-specific double-stranded DNA binding; DNA-binding transcription factor activity, RNA polymerase II-specific; DNA-binding transcription factor activity; sequence-specific DNA binding
Biological process: negative regulation of transcription by RNA polymerase II; animal organ morphogenesis; cell differentiation; regulation of transcription by RNA polymerase II; transcription by RNA polymerase II; regulation of DNA-templated transcription
Cellular component: nucleoplasm; chromatin; nucleus
Genetic constraint (gnomAD): Loss-of-function variants: 43 observed, 40.08 expected, observed/expected ratio (o/e) 1.07, 90% interval 0.84 to 1.38. The upper end of that interval is the gene's LOEUF score, 1.38, which puts it in group 5 of 6, group 1 being the genes least tolerant of losing a copy. Missense variants: 431 observed, 429.47 expected, observed/expected ratio (o/e) 1, 90% interval 0.93 to 1.09. Synonymous variants: 194 observed, 174.68 expected, observed/expected ratio (o/e) 1.11, 90% interval 0.99 to 1.25.
Homologues: Orthologues: chimpanzee ETV7 (99% identical), macaque ETV7 (85% identical), pig ETV7 (73% identical), dog ETV7 (70% identical), rabbit ETV7 (55% identical), zebrafish etv7 (45% identical), tropical clawed frog XB5809687 (32% identical). Paralogues in human: ETV6 (45% identical), ETS1 (23% identical), ERG (23% identical), ETS2 (21% identical), FLI1 (21% identical), SPDEF (19% identical), GABPA (19% identical), ETV1 (18% identical), ELF1 (17% identical), ETV5 (17% identical), EHF (17% identical), ELF2 (17% identical), and 16 more.
Diseases named in the same sentence as ETV7 in open-access papers:
ETV7 is named in the same sentence as 38 diseases in open-access papers, as found by Europe PMC text mining. Sharing a sentence is not in itself a finding about the gene and the disease. The quoted sentences say what the papers report.
breast carcinoma (9 papers, 2021 to 2025). "In breast cancer patients, the low expressions of ETV7-repressed interferon signature genes are associated with worse prognoses, suggesting that CSC-mediated suppression of interferon response is correlated with patient’s poor outcomes." (PMID 35455671, 2022). "Lastly, we show that the expression of the IFN-responsive genes repressed by ETV7 could have prognostic value in breast cancer, as low expression of these genes was associated with a worse prognosis." (PMID 34315857, 2021). "Therefore, we propose a novel role for ETV7 in breast cancer stem cells’ plasticity and associated resistance to conventional chemotherapy and radiotherapy, which involves the repression of a group of IFN-responsive genes, potentially reversible upon IFN-β treatment." (PMID 34315857, 2021). "These networks reveal the importance of the therapeutic modulation of PI3K/AKT/MTOR, ETV7, and YAP/TAZ, as they alter several oncogenes and cellular pathways and that can cause several diseases (including breast cancer); details given below." (PMID 38791386, 2024). "Subsequently, it was found that ETV7 controls the population of cancer stem cells in breast cancer and decreases the response to 5-fluorouracil along with radiotherapy." (PMID 38200280, 2024). "ETV7 also mediates the resistance to doxorubicin through downregulation of DNAJ heat shock protein family (Hsp40) member C15 (DNAJC15) in breast cancer." (PMID 38200280, 2024). "This also demonstrates that our observed VD3-GNP-mediated downregulation of YAP, TAZ, and ETV7 is newly found in breast cancer cells." (PMID 38791386, 2024). "Downregulating ETV7 with VD3-GNPs can potentially control breast cancer stemness, inflammation, and chemoresistance." (PMID 38791386, 2024). "It is known from the literature that the increased expression of ETV7 has also been detected in breast cancer patients and it correlated with breast cancer aggressiveness." (PMID 37041130, 2023). "In both cohorts, we showed an increase in ETV7 levels in breast cancer tissues compared to normal tissues." (PMID 37041130, 2023). "The transcription factor ETV7 is an oncoprotein that is up-regulated in all breast cancer (BC) types." (PMID 37041130, 2023). "In the same study, we uncovered that breast cancer cells stably over-expressing ETV7 develop resistance to doxorubicin by repressing the DNAJC15 gene, thereby increasing the expression of ABC pumps and leading to the increased efflux of the doxorubicin." (PMID 37041130, 2023). "In 2016, Piggin and colleagues reported an increased expression of ETV7 in all types of breast cancer compared to normal breast tissue." (PMID 37041130, 2023). "In this study, we demonstrate that ETV7 plays a role in the inflammatory response in breast cancer-derived cell lines." (PMID 37041130, 2023). "We confirmed that in breast cancer cells over-expressing ETV7, the repression of TNFRSF1A decreased the activation of NF-κB both in the basal state and upon the stimulation with TNF-α." (PMID 37041130, 2023). "Studies performed in our laboratory also demonstrated that different DNA-damaging agents up-regulated the expression of ETV7 in breast cancer cells." (PMID 37041130, 2023). "We have recently demonstrated that ETV7 promoted breast cancer progression by increasing cancer cell proliferation and stemness and was also involved in the development of chemo- and radio-resistance." (PMID 37041130, 2023). "Firstly, we analyzed the expression of ETV7 in breast cancer patients compared to normal breast tissue, using samples from TCGA and a private cohort, including ER-positive and triple-negative breast cancer patients." (PMID 37041130, 2023). "In this study, we further demonstrated the role of ETV7 in breast cancer cell resistance to another chemotherapeutic drug, 5-fluorouracil (5-FU) and radiotherapy." (PMID 34315857, 2021).
breast carcinoma (continued). "Lastly, we identified a gene signature of ETV7 downregulated genes endowed with prognostic relevance in breast cancer patients, suggesting a role for ETV7 and for this set of genes as possible biomarkers for BC prognosis." (PMID 34315857, 2021). "We first evaluated the sensitivity of the cells to 5-FluoroUracil (5-FU), a commonly used breast cancer chemotherapeutic drug which, similarly to Doxorubicin, is also able to induce ETV7 expression in breast cancer cells." (PMID 34315857, 2021). "Recently, Piggin and colleagues reported an average higher level of ETV7 expression in tissues from all the breast cancer subtypes compared to normal breast tissues, with a correlation of ETV7 expression and breast cancer aggressiveness." (PMID 34315857, 2021). "In this work, we expanded the effects of enhanced ETV7 expression on breast cancer progression and resistance to conventional anti-cancer drugs." (PMID 34315857, 2021). "Our data strengthen these observations and provide a novel role for ETV7 in breast cancer stem-like cell plasticity." (PMID 34315857, 2021). "A recent report shows increased ETV7 expression in all types of breast cancer, compared to normal breast tissue, along with other cancers, while ETV7 expression is correlated with tumor aggressiveness and stemness, though its therapeutic downregulation has not yet been seen." (PMID 38791386, 2024). "A similar mechanism may downregulate PI3K, AKT, and ETV7 levels and thereby reduce breast cancer cells’ invasiveness via the proposed VD3-GNP (24 h) treatment." (PMID 38791386, 2024). "Thus, we were intrigued to understand if ETV7 affects the expression of TNFRSF1A also in breast cancer patients." (PMID 37041130, 2023). "Furthermore, we demonstrated that the knock-down of ETV7 restored the expression of TNFRSF1A in several breast cancer-derived cellular models." (PMID 37041130, 2023). "In addition, ETV7 modulates the plasticity of breast cancer stem cells, hence reducing the sensitivity of cancer cells to some anti-cancer drugs (e.g., doxorubicin, 5-fluorouracil)." (PMID 37041130, 2023). "However, the role of ETV7 in breast cancer immunity and inflammatory processes remains to be investigated." (PMID 37041130, 2023). "Therefore, in this study, we focused on deciphering the role of ETV7 in breast cancer immunity and inflammatory response." (PMID 37041130, 2023). "Interestingly, in a private cohort of breast cancer patients, with triple-negative breast cancer patients’ subgroup we demonstrated an inverse correlation between the expression of ETV7 and TNFRSF1A." (PMID 37041130, 2023). "ETV7 promotes the resistance of breast cancer cells to chemotherapy and radiotherapy." (PMID 36324511, 2022). "Notably, an interferon-responsive gene signature is downregulated in ETV7-expressing breast cancer cells." (PMID 35455671, 2022). "We may speculate that the ETV7-dependent repression of the IFN-responsive genes could drive a more aggressive form of breast cancer, which according to our preliminary data, could possibly be responsive to IFN-β treatment." (PMID 34315857, 2021). "Recently, it was shown that the expression of ETV7 is significantly higher in breast cancer tissues compared to normal breast, suggesting a possible role for ETV7 in breast cancer pathogenesis; however, the functions and impact of ETV7 expression in breast cancer are still to be elucidated." (PMID 34315857, 2021). "Thus, the over-expression of ETV7 seems to drive a strong polarization of the analyzed breast cancer cells toward a more cancer stem-like cell phenotype represented by the CD44+/CD24− population." (PMID 34315857, 2021). "Interestingly, both MCF7 and T47D cells over-expressing ETV7 showed and increased expression of EpCAM, further strengthening our findings on the ETV7-mediated breast cancer stemness." (PMID 34315857, 2021).
breast carcinoma (continued). "As expected, we observed a robust and significant induction of ETV7 expression in response to both types of IFNs, with a peak of induction at 8 h for IFN-β and 24 h for IFN-γ, confirming that ETV7 is strongly responsive to IFNs also in the breast cancer-derived MCF7 cell line." (PMID 34315857, 2021). "In order to test whether the over-expression of ETV7 could confer resistance to other breast cancer treatments that act through a different mechanism of action, we examined the sensitivity to radiotherapy." (PMID 34315857, 2021). "In the light of these results, we propose a novel role for ETV7 as a regulator of breast cancer stem cell-like plasticity, which is mediated by the repression of IFN-stimulated genes and that can be partially reverted by the stimulation of IFN response with IFN-β." (PMID 34315857, 2021). "Based on these findings, we then examined whether the expression of ETV7-repressed IFN-responsive gene signature could have a prognostic value in breast cancer patients (TCGA cohort)." (PMID 34315857, 2021). "We previously showed that ETV7 over-expression in breast cancer cell lines could reduce the sensitivity to the chemotherapeutic drug Doxorubicin." (PMID 34315857, 2021). "However, the roles of ETV7 in breast cancer inflammation have yet to be studied." (PMID 37041130, 2023). "In addition, Piggin and colleagues demonstrated that ETV7 expression was significantly higher in breast cancer tissues compared to normal breast tissue, suggesting that ETV7 may play an important role in breast cancer development and progression." (PMID 37041130, 2023). "Moreover, anchorage-independent growth is considered a pro-tumorigenic feature, suggesting that the over-expression of ETV7 may induce pro-tumorigenic effects in breast cancer cells." (PMID 34315857, 2021). "Therefore, we hypothesized that, if ETV7 exerts its effect on breast cancer stem cell plasticity via the repression of IFN response genes, inducing the re-expression of these genes might possibly reverse the observed effects." (PMID 34315857, 2021). "Surprisingly, the VD3-GNP treatment is found to downregulate ETV7, the PI3K/mTOR/AKT cascade, along with the HIPPO pathway’s key proteins YAP and TAZ, which indicates its importance in controlling breast cancer aggressiveness." (PMID 38791386, 2024). "To better understand the transcriptional networks regulated by ETV7, in our previous study, we performed transcriptome analyses in two breast cancer-derived cell lines, MCF7 and T47D, that stably over-express ETV7 or empty counterpart." (PMID 37041130, 2023). "We also observed the transcriptional repression of the TNFRSF1A gene in other breast cancer cell lines SK-BR-3 and MDA-MB-231 upon transient over-expression of ETV7." (PMID 37041130, 2023). "Taken collectively, our data reveal that the altered expression of ETV7 can affect the sensitivity of BC cells to some anti-cancer agents (i.e., Doxorubicin, 5-FU, and radiotherapy) and that it may accomplish this task by modulating the breast cancer stem cells plasticity." (PMID 34315857, 2021). "Our VD3-GNP treatment of breast cancer cells (MCF-7 and MDA-MB-231) significantly reduces the aggressiveness (cancer cell migration and invasion rates > 45%) via the simultaneous downregulation of ETV7 and the Hippo pathway." (PMID 38791386, 2024). "Interestingly, we recently demonstrated that ETV7 repressed several IFN-responsive genes, increasing the subpopulation of breast cancer stem-like cells and, thus, the resistance to chemo- and radiotherapy." (PMID 37041130, 2023). "Furthermore, we were able to confirm the down-regulation of TNFRSF1A also in two other breast cancer-derived cell lines, SK-BR-3 and MDA-MB-231, upon the transient over-expression of ETV7." (PMID 37041130, 2023).
breast carcinoma (continued). "Knowing that TNF-α activates NF-κB signaling by binding to the TNFR1 receptor, we hypothesized that the ETV7-mediated repression of TNFRSF1A modulates the transcriptional activity of NF-κB in MCF7 and T47D breast cancer cells." (PMID 37041130, 2023). "In order to verify whether an inverse correlation between ETV7 and TNFR1 is also evident at the protein level in breast cancer patients, IHC analyses were conducted in a limited number of samples (3 patients) with invasive ductal carcinoma of the breast." (PMID 37041130, 2023). "The RNA-seq analysis we had previously conducted on the breast cancer-derived cells MCF7 and T47D over-expressing ETV7 or its empty counterpart supported our hypothesis by demonstrating the involvement of ETV7 in inflammation and immune responses." (PMID 37041130, 2023). "In addition, genome-wide transcriptional profiling has demonstrated that the combined treatment of MCF7 breast cancer-derived cells with the chemotherapeutic agent doxorubicin and the inflammatory cytokine TNF-α results in the synergistic induction of ETV7." (PMID 37041130, 2023). "In this work, we show a new role for ETV7, a transcriptional repressor member of the ETS family, in promoting breast cancer stem-like cells plasticity and resistance to chemo- and radiotherapy in breast cancer (BC) cells." (PMID 34315857, 2021). "Recent studies suggest that ETV7 controls breast cancer inflammation by controlling the TNF-α axis and cross-talking with STAT3—an inflammation regulator—suggesting that VD3-GNPs therapeutically alter these pathway markers via ETV7, which is a challenge for future studies." (PMID 38791386, 2024). "The objective of our study is to evaluate whether vitamin D3 conjugated to gold nanoparticles—VD3-GNPs—can reduce breast cancer aggressiveness and alter important cancer cellular pathway proteins (PI3K/AKT/mTOR, ETV7, and YAP/TAZ), so that the VD3-GNPs can be a cancer therapy." (PMID 38791386, 2024). "However, in the breast cancer cells over-expressing ETV7, we could not observe this regulatory mechanism, even when STAT3 was activated by the treatment with IL-6, thus demonstrating that there is a putative competitive relationship between ETV7 and STAT3 in the regulation of the TNFRSF1A gene." (PMID 37041130, 2023).